SPHK1 (sphingosine kinase 1)
Diseases named in the same sentence as SPHK1 in open-access papers (continued):
Sharing a sentence is not in itself a finding about the gene and the disease.
hepatocellular carcinoma (39 papers, 2013 to 2025). A malignant tumor that arises from hepatocytes. "Further, it was suggested that increased mRNA expressions of SphK1 and S1P lyase and reduced levels of S1P are associated with progression of hepatocellular carcinoma (HCC) with poorer differentiation and earlier recurrence." (PMID 29269995, 2017). "Specifically, the SphK1/S1P axis promotes hepatocellular carcinoma (HCC) cell proliferation, survival, and migration through the activation of the PI3K/AKT/mTOR and MAPK/ERK signaling pathways." (PMID 41234914, 2025). "Another study conducted on normal liver cells and hepatocellular carcinoma tissues revealed that cancer-specific SEs drive the overexpression of the oncogene SPHK1, leading to the proliferation and metastasis of hepatocellular carcinoma cells." (PMID 38443991, 2024). "In hepatocellular carcinoma, silencing BRD4 or MED1 repressed the transcription of SE-associated genes like SPHK1, E2F2, CCND1, MYCN, and MYC." (PMID 38443991, 2024). "In hepatocellular carcinoma cells, SphK1 inhibition by cinobufotalin induced ceramide production and Akt-mTOR inhibition." (PMID 37604912, 2023). "Research has suggested that SphK1 plays a role in chemotherapy resistance in breast, lung, colon, and hepatocellular cancer." (PMID 36909198, 2023). "Icaritin, a flavonoid, was observed to inhibit SphK1, resulting in cytotoxicity and enhanced apoptosis in hepatocellular carcinoma cell lines (Huh-7, HepG2, and KYN-2) that further hinders tumorigenesis." (PMID 33920887, 2021). "Overexpression of SPHK1 enzyme has also been reported in hepatocellular carcinoma and adrenocortical carcinoma tissues." (PMID 32170160, 2020). "The authors also observed that silencing SphK1 using siRNA inhibited the growth of hepatoma mediated by HBx in vitro and in vivo." (PMID 31783527, 2019). "For instance, SphK1 levels were shown to be increased in clinical hepatocellular carcinoma patient tissues as well as HBx-transgenic mice." (PMID 31783527, 2019). "Increased mRNA levels of hepatitis B virus (HBV) nonstructural protein, HBx, were positively correlated with an increase in SphK1 mRNA levels in clinical hepatocellular carcinoma patient tissues as well as HBx-transgenic mice." (PMID 31783527, 2019). "We showed that SPHK1 contributed to the hepatocarcinogenesis in DEN-induced mouse hepatoma models using SPHK1 knockout mice." (PMID 29360739, 2018). "A similar suppressive effect of peretinoin on the mRNA level of SPHK1 was also observed with another human hepatoma cell line, Hep3B." (PMID 29208982, 2017). "HULC promotes tumor angiogenesis in liver cancer through miR-107/E2F1/SPHK1 signaling and modulates abnormal lipid metabolism in hepatoma cells through a miR-9-mediated RXRA signaling pathway." (PMID 28427159, 2017). "We examined effects of peretinoin on expression, enzymatic and promoter activity of SPHK1 in a human hepatoma cell line, Huh-7." (PMID 29208982, 2017). "The mRNA level of SPHK1 was also increased in the liver in two different liver fibrosis-hepatoma mouse models." (PMID 29208982, 2017). "Mechanistically, HULC activated the promoter of SPHK1 in hepatoma cells through the transcription factor E2F1." (PMID 26540633, 2016). "HULC activates the transcription of SPHK1 through transcriptional factor E2F1 in hepatoma cells, leading to up-regulation of SPHK1." (PMID 26540633, 2016). "We next investigated the baseline activities of three key enzymes involved in sphingolipid metabolism – ASM, acid ceramidase (AC), and sphingosine kinase 1 (SPHK1) – in three commonly used human hepatoma cell lines: HepG2, Huh7 and Hep3B." (PMID 23724146, 2013). "In hepatomas cells, sphingosine kinase 1 (SPHK1) could induce EMT and promote cell invasion by enhancing the K63-linked ubiquitination of BECN1, thus accelerating CDH1/E-cadherin lysosomal degradation." (PMID 31272261, 2019). "Additionally, diethylnitrosamine-induced hepatoma was fewer and less frequent in SPHK1 knockout compared to wild-type mice." (PMID 29208982, 2017).
hepatocellular carcinoma (continued). "Interestingly, our data show that HULC is capable of promoting tumor angiogenesis through miR-107/E2F1/SPHK1 signaling in hepatoma cells." (PMID 26540633, 2016). "We found that overexpression of HULC (or depletion of HULC) could enhance (or decrease) the secretion of S1P from hepatoma cells into the medium by SPHK1." (PMID 26540633, 2016). "Data from different human hepatocellular carcinoma (HCC) cohorts showed that both SPHK1 and the S1P exporter ABCC1 were expressed at higher levels in aggressive HCC when compared with normal liver or cirrhotic tissue." (PMID 35163211, 2022). "Sphk1 has been shown to be involved in the pathogenesis of human hepatocellular carcinoma (HCC), and DMS can inhibit the effects of Sphk1." (PMID 31341536, 2019). "Sphingosine kinase 1 (SphK1), a key regulator of sphingolipid metabolites, is over-expressed in human hepatocellular carcinoma (HCC) and our previous studies have shown that SphK1 is important in liver injury." (PMID 29643998, 2018). "SphK1 facilitated autophagy and induced the EMT by promoting lysosomal degradation of CDH1/E-cadherin in hepatoma cells." (PMID 36909198, 2023). "And the involvement of the SPHK1 in CSC functioning has been recently investigated in several malignancies, including glioblastoma, melanoma, hepatocellular carcinoma, and breast adenocarcinoma." (PMID 37999228, 2023). "In another study, the comparison of SphK1 expression levels in tumor tissues and adjacent normal tissue samples revealed that patients with hepatocellular carcinoma (HCC) had significantly upregulated SphK1 levels, and higher SphK1 expression was correlated with shorter overall survival times." (PMID 35201458, 2021). "Further study is required to determine the effects of SphK1 expression and activity on HBV replication and evaluate the viability of SphK1 inhibition as a potential therapeutic for hepatocellular carcinoma or chronic HBV infection." (PMID 31783527, 2019). "Although we showed crucial roles for SPHK1 in a DEN-induced hepatocarcinogenesis model in this study, further validation is needed in different mouse models of liver fibrosis and hepatoma." (PMID 29208982, 2017). "Additionally, Sphingosine kinase 1 mediates Beclin1-induced autophagy and lysosomal degradation of E-cadherin, promoting EMT in HepG2 hepatoma cells." (PMID 38898476, 2024). "Patients with hepatocellular carcinoma were shown to have increased SphK1/2 when compared with non-cancerous patients and increased SphK1 specifically was associated with a poorer prognosis." (PMID 32528896, 2020). "We then showed that the expression levels of SPHK1 were higher in clinical hepatoma tissues relative to non-tumor tissues." (PMID 26540633, 2016).
melanoma (38 papers, 2011 to 2026). A malignant, usually aggressive tumor composed of atypical, neoplastic melanocytes. "First, we showed a new and undiscovered association between SPHK1 and PD-L1, which are crucial molecules in tumor occurrence and development, particularly in malignant melanoma with high immunogenicity." (PMID 36050478, 2022). "We next sought to explore the downstream signaling pathway underlying the SPHK1-induced regulation of tumor PD-L1 expression levels in melanoma." (PMID 36050478, 2022). "Expression of SPHK1 in melanoma cells was associated with shorter survival in metastatic melanoma patients treated with anti-PD-1 ICB." (PMID 35163211, 2022). "Of interest is the finding that degradation of ceramide into sphingosine via the acid ceramidase (AC), followed by phosphorylation of sphingosine to S1P, by sphingosine kinase 1 (SphK1), is associated with melanoma progression." (PMID 33121001, 2020). "Melanoma antigen-specific T cells deficient for Sphk1 (pMel-SphK1−/− T cells) were shown to maintain a central memory phenotype and have a reduced propensity to differentiate into Treg as compared to wild-type T cells (pMel T cells)." (PMID 32858889, 2020). "SIRT1, SIRT6 and SPHK1 induced EMT by up-regulating autophagy-linked lysosomal degradation of E-cadherin in melanoma and hepatocellular cells via Beclin 1-E-cadherin cascade respectively." (PMID 33425768, 2020). "The SK type 1 isoform (SK1), encoded by the SPHK1 gene, which is overexpressed in numerous human tumors, including melanoma, leads to increased levels of S1P8,9." (PMID 31974367, 2020). "In another example of complex feedback between cancer cells and their microenvironment, SPHK1-S1P signalling from melanoma cells up-regulates SPHK1 expression in tumour associated fibroblasts." (PMID 24970218, 2014). "Interestingly, SphK1 expression in AT and S1P levels in serum were shown to increase with obesity; however, their role in the association between obesity and melanoma remains to be demonstrated." (PMID 33121001, 2020). "Consequently, Sphk1-deficient T cells adoptively transferred into C57BL/6 mice are more efficient to control B16F10 melanoma growth as compared to wild-type T cells." (PMID 33121001, 2020). "Moreover, we recently showed that high SphK1 expression in melanoma cells was associated with shorter progression-free and overall survivals in melanoma patients treated with anti-PD-1-based immunotherapy." (PMID 32858889, 2020). "SphK1 shows increased expression and/or activity in melanoma cells compared to normal melanocytes, in both cell lines and human tissue samples." (PMID 41596686, 2026). "Melanoma cells reduce ceramide to avoid cell death by altering enzymes like AC, SphK1, and GlCer synthase." (PMID 41596686, 2026). "First, previous study showed that the SpHK1-mediated high expression of PD-L1 in melanoma promotes the immune resistance and that this dysfunction can be rescued by PD-1 blockade." (PMID 41513624, 2026). "SPHK1 is upregulated in multiple types of cancer including melanoma, papillary thyroid carcinoma, non-small cell lung cancer, triple-negative breast cancer, and colorectal cancer." (PMID 36672428, 2023). "In melanoma cells, extracellular S1P activated NFκB, and this was correlated with expression of actin-binding protein FlnA, an interaction partner of SPHK1 and TRAF2." (PMID 36672428, 2023). "Targeting sphingosine kinase 1 (SK1) significantly enhanced the ICI response in mouse models of melanoma, breast cancer and colon cancer." (PMID 36038892, 2022). "Correlation analyses suggested a significant difference in PD-L1 membrane expression between the melanoma population with high or low cytoplasmic expression of SPHK1 (p = 9.85 × 10−4), or with high or low nuclear expression of MTA3 (p = 5.48 × 10−3)." (PMID 36050478, 2022).
melanoma (continued). "Consistent with our observations, the suppression of SPHK1 in melanoma cell lines in vitro, either by treatment with PF543 or with an SPHK1-targeting short interfering RNA (siRNA), produced reductions in the MTA3 and c-Myc expression levels." (PMID 36050478, 2022). "It has been reported that elevated sphingosine-1-phosphate (S-1-P) levels resulting from increased activity of sphingosine kinase-1 (SPHK1) occur in melanomas." (PMID 35335379, 2022). "SPHK1- or MTA3-OE cells showed significantly increased melanoma growth compared with B16F10CTL cells." (PMID 36050478, 2022). "In HeLa, HEK 293, and A7 melanoma cells, it was shown that cytoplasmic intracellular S1P generated by SPHK1 is critical for the canonical NF-κB activation pathway by TNF-α—which is necessary for inflammatory immune processes and anti-apoptotic functions." (PMID 35565311, 2022). "Functionally, we demonstrated that the inhibition of SPHK1 significantly suppressed tumor growth by promoting antitumor immunity in immunocompetent melanoma mouse models and tumor T-cell cocultures." (PMID 36050478, 2022). "In summary, we elucidated an emerging functionality of SPHK1, identified SPHK1-mediated immunosuppression established by transcriptional regulation of PD-L1 in malignant melanoma and demonstrated a novel mechanism of PD-L1 expression." (PMID 36050478, 2022). "We have elucidated an emerging functionality of SPHK1, identified SPHK1-mediated immunosuppression established by transcriptional regulation of PD-L1 in malignant melanoma and demonstrated a novel mechanism of PD-L1 expression." (PMID 36050478, 2022). "Consistently, in peripheral T cells, SPHK1-generated S1P binds PPARγ for its transcriptional activation, and the inhibition of SPHK1/S1P/PPARγ signaling ameliorates antitumor immunity against mouse melanoma." (PMID 35565311, 2022). "To this end, we first generated poorly immunogenic B16F10 mouse melanoma cells stably overexpressing SPHK1 or MTA3." (PMID 36050478, 2022). "In this respect, it was recently showed that SphK1 expression constitutes a potential biomarker to predict melanoma progression and resistance to anti-PD-1 therapy." (PMID 33121001, 2020). "We reported that melanoma SphK1 plays a key role in the recruitment and phenotypic switch of TAM notably promoting their commitment to a pro-tumoral M2-like phenotype." (PMID 32858889, 2020). "In mice, SphK1 knockdown in melanoma tumours potently reduced the production of a number of immunosuppressive cytokines including TGF-β, limiting Treg tumour infiltration." (PMID 32858889, 2020). "Consistent with the high levels of SphK1 reported melanoma cells, a shift of the S1P-ceramide balance towards S1P production was observed." (PMID 33121001, 2020). "SGPP1 down-regulation has also been demonstrated in hepatocellular carcinomas, and a panel of melanoma cell lines, coinciding with up-regulated SPHK1." (PMID 24970218, 2014). "In addition, SPHK1 axis holds the potential to predict melanoma patient outcomes in response to anti-PD-1 mAb therapies." (PMID 41513624, 2026). "SPHK1 inhibitors (e.g., PF-543) and S1P receptor modulators (e.g., fingolimod) restore ceramide-mediated apoptosis and reduce T-cell exhaustion, improving the melanoma response to immunotherapies." (PMID 41596686, 2026). "Prior studies conducted by SubbaRao demonstrated that targeting SPHK1 could reduce pAkt expression and arrest cells in the G0/G1 phase of the melanoma cell cycle, thereby decreasing tumor cell proliferation and inducing apoptosis 37-38." (PMID 39629135, 2024). "Moreover, anti-PD-1 and PF-543 (SPHK1 inhibitor) combinations improve the control of melanoma tumor growth." (PMID 35565311, 2022). "Importantly, melanoma cells with high SPHK1 and MTA3 expression were found to be highly sensitive to anti-PD-1 mAb-mediated tumor cytotoxic effects in vivo." (PMID 36050478, 2022).
melanoma (continued). "Rather, SPHK1-deficient T cells showed a sustained memory response and reduced differentiation to Tregs independent of S1PR signaling, which resulted in activity of T cells against murine melanoma cells and synergy with ICB." (PMID 35163211, 2022). "In addition, MTA3 was first found to be a potential target of SPHK1 and to participate in the transcriptional regulation of PD-L1 in malignant melanoma." (PMID 36050478, 2022). "To test this hypothesis, we established melanoma cell lines stably overexpressing Flag-SPHK1 driven by lentiviral vectors and subsequently knocked down MTA3." (PMID 36050478, 2022). "Additionally, inhibiting SPHK1 enhances the metabolic activities of T cells and improves their antitumor functions against murine melanoma." (PMID 35565311, 2022). "Moreover, ablation of SPHK1 in melanoma cells lead to a shift of macrophages with tumor-promoting to macrophages with tumor-suppressive phenotype markers, which was coupled to T cell recruitment and activation." (PMID 35163211, 2022). "Its level of expression seemed highest in metastatic states, and therefore, the progressive state of melanoma was directly correlated to the levels of SPHK1 gene, where models with higher levels of SPHK1 expression revealed shorter progression free survival when treated with anti-PD1 therapy." (PMID 33670011, 2021). "This phenomenon could be indirect in melanoma cells as the SphK1/S1P pathway is able to stimulate TGF-β1 production, which may trans-activate S1P2 and S1P3." (PMID 32858889, 2020). "Moreover, SphK1 knockdown by siRNA decreased anchorage-dependent and -independent growth of human melanoma cells." (PMID 32858889, 2020). "Similarly, targeting SphK1 using shRNA in B16F10 or Yumm 1.7 murine melanoma cells reduced tumour growth in syngeneic mice." (PMID 32858889, 2020). "By reducing ceramide levels, AC, in concert with SphK1, favours melanoma cell proliferation." (PMID 32858889, 2020). "The Wnt/β-catenin pathway is a well-known activator of MITF expression in melanoma cells, and deactivation correlates with a higher metastatic potential, suggesting a role of the Sphk1/S1P axis in melanoma aggressiveness through MITF downregulation via the Wnt/β-catenin pathway." (PMID 33121001, 2020). "Therefore, our findings indicate that Sphk1 inhibition and Sphk2 activation are important for cisplatin mediated apoptosis in PKCδ deficient B16F10 melanoma cell." (PMID 30701020, 2018). "In addition, SphK1-expressing melanoma cells secreted factors required for fibroblasts to myofibroblasts differentiation, strongly indicating that SphK1 was crucial for communication between stromal and cancer cells in melanoma." (PMID 27800303, 2016). "There are also evidences that Bcl-2 overexpression may stimulate Sphk1 expression and activity in human melanoma cells." (PMID 25056275, 2015). "Mutant B-Raf, the most common genetic lesion in melanoma, also up-regulates SPHK1." (PMID 24970218, 2014). "In addition, the data from Albinet and colleagues have introduced the concept that SPHK1 could initiate fibroblast differentiation in melanoma and lead to tumor metastasis." (PMID 36050478, 2022). "A number of Sphk1 inhibitor studies have demonstrated that Sphk1 inhibitor induces cell death, cell-cycle arrest and apoptosis in human cancer cells; however, no available information exists showing the ability of inhibiting migration and invasion of human melanoma cells." (PMID 35335379, 2022). "Moreover, due to the propensity of melanoma cells to deplete ceramide by modifying the expression of AC, SphK1 and GlCer synthase, inhibitors targeting these enzymes have exhibited therapeutic potential by tipping the balance towards ceramide accumulation to promote cell death." (PMID 33121001, 2020).